MIR6743 (microRNA 6743)
Synonyms: hsa-mir-6743
Gene: MicroRNA gene on chromosome 11 (209,336 to 209,406, forward strand). Ensembl gene ENSG00000283920.
Homologues: Orthologues: chimpanzee MIR6743 (100% identical).